IL6 (interleukin 6)
Diseases named in the same sentence as IL6 in open-access papers (continued):
Sharing a sentence is not in itself a finding about the gene and the disease.
infection (continued). "NMN treatment can reduce NF-κB signaling pathway activation in bone marrow-derived macrophages (BMDM) after hvKP infection, as well as the transcription of Il6, Il1b, Tnf, and Cxcl2." (PMID 40742124, 2025). "Analyses of sera demonstrated elevated levels of the cytokines IL-6 and IL-10 in the in wild-type B6 mice compared to C3 knockout mice following infection with the Ig::Tn strain (respectively)." (PMID 40586810, 2025). "Although transcription of IL-1α, IL-1β, IL-6, and IL-15 genes was substantially upregulated, overall cytokine responses to infection with VR-2332 were insignificant." (PMID 40302751, 2025). "Cytokines classically induced in human infections with SARS-CoV-2, such as IL-6, IL-8, and IP-10, were all induced by all variants, demonstrating the fidelity of the HNO-ALI model." (PMID 41157615, 2025). "Th-17 differentiation is triggered by IL-6 and IL-23 and produces IL-17A, IL-17F, and IL-22 cytokines that further recruit innate immune cells to the site of infection." (PMID 40586608, 2025). "Although brain inflammation was limited in our model, cytokines, including G-CSF, CXCL10, CXCL1, IL-6, and IL-1β, were already increased in the periphery by day 3 post-infection, despite a low to undetectable viral load." (PMID 41472308, 2025). "Similar to our findings, in a recent study ICIS demonstrated a diagnostic performance for early infection detection at admission, with an AUC of 0.958, outperforming CRP, PCT and IL6." (PMID 40471473, 2025). "This extract significantly reduced inflammation and prevented infection by inhibiting the release of pro-inflammatory cytokines such as TNF-α and IL-6, thereby protecting mice from lung injuries associated with endotoxin-induced septic shock." (PMID 40144662, 2025). "The levels of serum IL-6 were higher on day 4 than on days 2 and 6 post-infection in both groups of mice." (PMID 40377310, 2025). "Regarding inflammatory response, the untreated group exhibited significantly elevated levels of pro-inflammatory cytokines TNF-α and IL-6, reflecting a strong infection-induced inflammatory response." (PMID 40149043, 2025). "The indispensable roles for innate cytokines during primary infection are well appreciated, but, more importantly, early IL-6 is paramount for the expansion of primed CD4+ T cells and enhances the production of IL-2, TNF, and IFN-γ during secondary infections." (PMID 40279312, 2025). "This clinical condition resembles what we observed in our infection model, where the modulation of IL-6, IL-12 and IFN-γ is crucial for the survival of infected mice." (PMID 41156807, 2025). "On the other hand, IL-6, a leukocytic endogenous mediator, has a much lower expression level after infection." (PMID 39888929, 2025). "Infection with the wild-type strain led to increases in the levels of the inflammatory cytokines IL-6, TNF-α, and IL-10, but deletion of the porV locus significantly reduced the levels of these factors (P ≤ 0.01)." (PMID 40484959, 2025). "Previous studies have demonstrated that the early depletion of IL-6 during infection leads to an increased viral load, more severe inflammatory responses, and greater lung damage." (PMID 40732729, 2025). "In the spleen, the increase in CFU increased with levels of IL-6 (0.82) and TNF-α (0.83), which shows that the increase in CFU in the spleen is associated with the immune profile previously observed during infection by this fungus." (PMID 41156648, 2025). "By contrast, the gingipains absence in the W83 ∆KRAB mutant did not affect the secretion of other cytokines (i.e., TNF-α and IL-6) after 24 h of infection." (PMID 39936030, 2025). "Plasma was analyzed by ELISA for IL-6,an important mediator ofthe acute phase response to infection, and by colorimetric assay forlactate dehydrogenase (LDH) activity and alanine transaminase activity(ALT), markers for organ damage." (PMID 40641435, 2025).
infection (continued). "As expected, infection with both pathogens resulted in robust IL-6 and significant IFN-β production by all glial populations compared to the cells treated with the negative-control siRNA." (PMID 41341589, 2025). "The lung, as the site of infection, showed consistent increases in IL-1α and IL-6, paralleling serum responses in coinfected mice." (PMID 41226526, 2025). "We identified 86 cases secondary to infection with stored biological samples which were subsequently assayed for IL-6 levels." (PMID 40819633, 2025). "This is reflected in the rapid activation of immune responses through elevated IL-6 levels, enhancing their resistance to infections." (PMID 39858197, 2025). "And it is a generally acknowledged fact that IL-6 is a critical prominent proinflammatory cytokine released during infection or tissue injury that contributes to both innate and adaptive immune responses." (PMID 41293456, 2025). "During adverse conditions like infections, inflammatory cells in the body rapidly accumulate to produce IL-6, leading to an increase in its levels." (PMID 41137299, 2025). "The median pre-infection biomarker level was higher in each instance, and this difference was significant for IL-6 (p = 0.0088) and trending for IL-21, IL-5 and fractalkine (p = 0.0192, 0.0503 and 0.0533 respectively)." (PMID 40862133, 2025). "Further, Ptpn2∆IEC mice displayed lower IL-22, IL-6, IL-17A cytokine expression post mAIEC infection compared to Ptpn2fl/fl controls." (PMID 40955058, 2025). "Nearly all cytokines and chemokines peaked around 14 hours post-infection, except for IL-6 which peaked at 2 hours post-infection, and they returned to baseline by 48h." (PMID 40766470, 2025). "IL-6 expression is markedly increased at day 1 post-infection compared with baseline for both adult and geriatric cotton rats, as previously reported." (PMID 39818970, 2025). "Though, IL-6-secretion appeared differentially regulated in age groups in response to P. gingivalis-infection." (PMID 40581654, 2025). "First, although improving the diagnosis efficacy of intracranial infections, these indicators like CI, CSF PCT, or CSF IL-6 and their combinations cannot directly indicate exact etiological infection as metagenomic sequencing does." (PMID 40223136, 2025). "Patients receiving ozone therapy demonstrate reductions in inflammatory markers (CRP, IL-6, D-dimer), improved redox balance, decreased infection frequency, and better overall immune performance." (PMID 41614780, 2025). "Monocytes, macrophages, T cells, B cells, endothelial cells and fibroblasts are the various cells that produce IL-6, in response to infection, injury and other inflammatory stimuli." (PMID 41302151, 2025). "SARS-CoV-2 spike protein at 12 μg/ml concentration showed robust induction of IL-6 mRNA expression in infection group when compared with vaccination group." (PMID 40329195, 2025). "Gene expression of pro-inflammatory cytokines IL-1β, IL-2, IL-4, and IL-6, as well as IFNγ was significantly upregulated in nasal turbinates in response to infection with all VOCs, compared to mock-infected hamster tissues." (PMID 40295859, 2025). "In our study, in women with PCOS and confirmed infection with any atypical pathogen (n = 196), we analyzed the levels of proinflammatory cytokines, IL-1 β a, IL-6 and TNF-α." (PMID 40647668, 2025). "Subtypes ST2 and ST6 are notably correlated with increased proteolytic activity, upregulated interleukin-6 (IL-6) secretion, and symptomatic infection." (PMID 41347242, 2025). "In the event of infection, toll-like receptors identify bacteria and viruses, which results in the direct or indirect stimulation of IL-6 and other inflammatory cytokines." (PMID 40063597, 2025). "The expression levels of IL-6 and IL-1β in the mouse serum were assessed at 12, 24, and 48 h post-infection." (PMID 40230687, 2025).
infection (continued). "With regard to safety, overcoming the serious gastrointestinal events and infections observed with tocilizumab and PF-04236921 remains the main concern in the future development of IL-6 inhibitors." (PMID 39857830, 2025). "Specifically, for each unit increase in IL-6, the probability of infection with MP increases by 1.835 times." (PMID 41137299, 2025). "CRP is produced as a response to an infection or trauma, upregulated by cytokines, especially IL-6, but also IL-1 and TNF." (PMID 41007875, 2025). "Salivary IL-6 is a cytokine, an important signaling molecule in the immune system, which plays a key role in inflammation and the body’s response to infections." (PMID 40002706, 2025). "Supernatants were collected 24 hrs after infection and levels of four pro-inflammatory cytokines (TNF-α, IL-1β, IL-8, and IL-6) associated with infection were assessed." (PMID 41550953, 2025). "In contrast, IL-6 and IL-10 demonstrated superior discriminative power, with AUC values exceeding 0.8 for predicting severe infection." (PMID 40647525, 2025). "This immune response involves interleukin-6 secretion by activated macrophages following infection, which inhibits Alb production in the liver while stimulating immunoglobulin production, resulting in reduced Alb and elevated Glb levels." (PMID 40943760, 2025). "Initially, the immune response focused on combating the infection, evidenced by strong correlations among inflammatory cytokines like IL-1β, IL-6, IL-8, TNFα, and IFNγ." (PMID 40557167, 2025). "It is suggested that the involved pathological processes result in increased levels of proinflammatory cytokines, such as TNF-α, IL-1 and IL-6, among others, in response to infection." (PMID 40647668, 2025). "By 1 week post-infection, high levels of cytokines such as IFN-γ, IL-12, IL-6, and RANTES can be detected in the serum of susceptible mice." (PMID 40606156, 2025). "Initial studies examining IL-6 levels in the cerebrospinal fluid in SIDS disclosed elevated levels compared to controls, with about half of the SIDS victims exhibiting IL-6 levels within the same range as infants dying from severe infection." (PMID 40013115, 2025). "IL-6 is involved in inflammation in response to infection and the regulation of regenerative, metabolic, and neural processes." (PMID 39830087, 2025). "Coefficients (Β) using the optimal λ were calculated for the variables of the model: age (B = 0.05, SE: 0.01), admission GCS (B = −0.29, SE: 0.07), infection (B = 0.38, SE:0.55) and day-0 IL-6 (B = 0.05, SE = 0.005)." (PMID 40713822, 2025). "This response is characterized by the production of cytokines such as IL-4, IL-5, IL-6, IL-10, and IL-13, which deactivate infected macrophages and allow parasite dissemination at infection sites and internal organs." (PMID 40391226, 2025). "In this study, after the administration of AB-WE to goldfish and following pathogen infection, the expression of inflammation-related factors (IL-6, IL-8, TNF-α, and IL-1β) displayed a significant reduction (p < 0.05) in visceral tissues." (PMID 40805047, 2025). "When we knocked out C3, we found that inflammatory cytokines such as TNF-α, IL-1β, IL-17A, and IL-6 were upregulated on day 1 post-infection." (PMID 40008883, 2025). "Compared with those in the WT infection group, the expression levels of common proinflammatory factors in the ΔL-lectin group were significantly lower, including IFNγ, IL1β, IL6, IL8, and TNFα." (PMID 40076391, 2025). "Specifically, IL-6 plays a pro-inflammatory role in the acute phase response to infection and injury, promoting inflammation by inducing the production of acute phase proteins and activating other immune cells." (PMID 41327470, 2025). "Studies that examine inflammatory biomarker levels often exclude children with an infection that coincides with the time of blood collection because levels of IL-6 and CRP increase in response to acute infection but return to baseline afterwards." (PMID 40605248, 2025).
infection (continued). "During an infection, immune cells such as macrophages, neutrophils, dendritic cells, and lymphocytes produce excessive IL-6." (PMID 40571942, 2025). "The initial response of DCs to CPXV infection involves the secretion of inflammatory cytokines such as TNF-α and IL-6, which facilitate the recruitment of other immune cells to the site of infection." (PMID 40872644, 2025). "IL‐6, a multifunctional cytokine with a four‐helix‐bundle structure, significantly contributes to the acute phase response and infection defense mechanisms within the liver." (PMID 40728098, 2025). "Interleukin 6 (IL-6), produced by immune cells, is crucialin promotingT cell trafficking to infection and inflammation sites, influencingvarious physiological and pathological processes." (PMID 39471283, 2025). "When homeostasis is disrupted by infection or tissue damage, IL-6 is promptly produced and aids the host in counteracting this emergency stress by activating acute-phase and immune responses." (PMID 40530673, 2025). "Elevated inflammatory markers, including CRP and IL-6, were also observed, reflecting infection-related responses." (PMID 41210029, 2025). "IL-17 is a pro-inflammatory cytokine that promotes the expression of IL-6 and granulocyte colony-stimulating factor (G-CSF), which in turn enhances neutrophil recruitment to the site of infection and stimulates granulopoiesis." (PMID 40573262, 2025). "Even a short preoperative course with synbiotics reduced IL-6 and CRP levels and also reduced the risk of infection by 85%." (PMID 40671981, 2025). "To further demonstrate that the IL-6–Jak2–Stat3 axis is involved in Th17 cell development during PmA infection, we used IL-6-KO mice and recombinant IL-17A." (PMID 41402924, 2025). "Infection by T. gondii increased IL-6 levels in the control group compared to uninfected/untreated cells (**** p < 0.0001)." (PMID 40871442, 2025). "IL-6 is produced by a number of cells including T cells, MCs, and macrophages in response to infection and acute inflammation." (PMID 40529483, 2025). "IL-6 is produced rapidly and transiently in response to infection and tissue injury and promotes host defense by stimulating the acute phase response, hematopoiesis, and immune response." (PMID 40218416, 2025). "Proinflammatory cytokines IL-6 and IL-1α were significantly upregulated post-infection, while IL-8 and CXCR1 were differentially expressed, indicating their involvement in neutrophil recruitment and immune modulation." (PMID 40453956, 2025). "Infection with G. parasuis elicits a pronounced inflammatory response, characterised by elevated levels of IL-1β, IL-6, TNF-α, and IL-17, which collectively contribute to tissue damage and systemic inflammation." (PMID 40665414, 2025). "Although CRP levels rise at a slower rate compared to IL-1, TNF-α, and IL-6, they start to increase within 4–6 h after the onset of inflammation or infection and typically reach peak levels within 24–48 h." (PMID 40584620, 2025). "For IL-6 inhibitors, IL-6 plays a role in inflammatory signaling that triggers symptoms including fever, which can mask the early signs of infection." (PMID 41357870, 2025). "Key parameters of infection (IL-6, TNFa, D-dimer, CRP and CD4+ T cell counts) were correlated (Spearman) with lipid concentrations at critical time points of infection and treatment." (PMID 40129985, 2025). "IL-6 has both pro- and anti-inflammatory properties and it is produced early during infection with mycobacteria which, can be found mainly at an infection site." (PMID 40547033, 2025). "HCoV-229E induced both IFN-β and IFN-λ transcription in infected Huh7 cells, but only at a late stage during infection, and a similar pattern was observed for the NF-κB-regulated IL-6 gene." (PMID 39940968, 2025). "IL-6 is a multifunctional cytokine secreted by monocytes, B and T lymphocytes, fibroblasts, and activated macrophages during infection and tissue damage." (PMID 40149596, 2025).
infection (continued). "During treatment with IL-6 inhibitors, 24 cytopenia events were reported, followed by 22 infection events." (PMID 40287866, 2025). "To further investigate the inflammatory response, we examined plasma levels of IL-1β, IL-6, and TNFα in mice following infection with either wild-type or ΔmsbB ST." (PMID 41304196, 2025). "SARS-CoV-2 infection triggers immediate cytokine release within hours, with IL-6 concentrations reaching 50–100 times baseline levels during peak response at 7–10 days post-infection." (PMID 40843696, 2025). "In the early days post-infection, innate immunity predominates, characterized by increased levels of inflammatory cytokines (e.g., IL-6 and TNF-α) in response to initial viral replication." (PMID 41357245, 2025). "Serum levels of TNF-α, IL-6, and IFN-γ are elevated in DFI patients and are closely associated with infection severity and prognosis." (PMID 40677522, 2025). "The same work described that BALB/c mice exposed to a low dose of LPS prior to IAV H1N1 (A/Fort Monmouth/1/1947) infection exhibited reduced weight loss, lung injuries, and respiratory levels of TNF-α, IL-6, and IL-18." (PMID 40565228, 2025). "After 14 days of infection, IL-1β, IL-6, and LITAF were significantly increased in the H9 group compared with the other groups (p < 0.05)." (PMID 40218416, 2025). "Consistent with prior reports, nutritional intervention significantly improved short-term nutritional and immune indicators (PA, Hb, TLC, IgA, IgG, IgM) and reduced inflammatory cytokines (IL-2, IL-6, TNF-α), thereby lowering infection risk." (PMID 41306668, 2025). "Initial infection triggers alveolar type II pneumocyte involvement, innate cell infiltration, and a cytokine cascade (IL-1, IL-6, IL-8, IL-12, IP-10, MCP-1), with concentrations often exceeding those in SARS and non-COVID ARDS." (PMID 41303146, 2025). "We did not observe a notable release of TNF-α, but all three FSSC species induced a higher release of IL-6 and IL-8 from infected hemi-cornea models than C. albicans, especially after 48 h of infection." (PMID 41186402, 2025). "To determine if TBC1D9’s role during hypervirulent infection extends beyond IL-6, we infected epithelial cells with GAS SSI-1 (M3) and measured the expression of IFN-β, TNF-α, IL-1β, and IL-8." (PMID 41306588, 2025). "IL-6 is an anti-inflammatory cytokine that plays a major role in the acute phase of protein production by hepatocytes in the case of infection." (PMID 40981112, 2025). "In contrast, untreated infection networks were dominated by inflammatory mediators (IL6, CXCL10, CCL2, VCAM1, SELE) and antiviral sensors (DDX58, OAS1, IFI44, IFI6), which reflect strong cytokine and interferon-driven immunity." (PMID 41480150, 2025). "Patients with hospital infections had significantly higher IL-6 levels at all time points (day 0: 51.98 pg/ml vs. 19.44 pg/ml, P < 0.001; day 3: 28.67 pg/ml vs 7.77 pg/ml, P < 0.001; day 7: 19.54 pg/ml vs. 5.71 pg/ml, P = 0.0011)." (PMID 40713822, 2025). "IL-6 is a very important cytokine in the early host response to infection, and an increase in IL-6 precedes an increase in CRP." (PMID 39755760, 2025). "IL6 is a key mediator of neuroinflammation and is released in response to inflammation, injury, or infection." (PMID 40940721, 2025). "In recent years, two additional biomarkers have emerged as potential tools for early detection of infection: Presepsin and IL-6." (PMID 40806991, 2025). "Monocyte activation with palmitate for 18 h before infection (referred to as priming) with different SARS‐CoV‐2 variants (B1, Delta, Omicron) led to an increased viral load and elevated gene expression of IL‐6 and IL‐1β in all variants tested." (PMID 40265287, 2025). "IL-6 is transiently upregulated during the early phases of infection and tissue injury, facilitating host defense mechanisms through the stimulation of acute phase responses, hematopoiesis, and immune activation." (PMID 40298808, 2025).